CD14 (CD14 molecule)
Diseases named in the same sentence as CD14 in open-access papers (continued):
Sharing a sentence is not in itself a finding about the gene and the disease.
HIV-1 infection (continued). "The findings are consistent with observations on decidual CD14+ cells and placental tissue obtained from the first trimester of pregnancy which were also permissive to R5 HIV-1 infection but to a lesser degree than peripheral blood macrophages." (PMID 23217137, 2012). "Increased levels of soluble CD14 (sCD14), secreted by CD14+ monocyte/macrophages in response to LPS, were observed in early HIV-1 infection and were found to be higher in those who progressed to AIDS." (PMID 22292110, 2011). "Taken together, we propose that SAMHD1 protects primary CD14+ monocytes from HIV-1 infection confirming SAMHD1 as a potent lentiviral restriction factor." (PMID 22174685, 2011). "Flow cytometry analysis showed that CD14+ cells are the main targets of HIV-1 infection in this system (6,09%)." (PMID 19543402, 2009). "We have shown that sialoadhesin is induced to high levels on CD14+ cells early after HIV-1 infection in vivo." (PMID 17330143, 2007). "An expansion of CD14+CD16+ monocytes has been observed after HIV-1 infection and other inflammatory conditions, while numbers of CD14++ monocytes do either not change, or decrease slightly, in agreement with our observations." (PMID 17330143, 2007). "Concluding, we have shown that early after HIV-1 infection, sialoadhesin is induced to high levels on CD14+ cells of the blood." (PMID 17330143, 2007). "CD14 is a coreceptor for LPS and its soluble form is a marker of monocyte activation, and represents an independent predictor of morbidity and mortality in people with HIV-1 infection." (PMID 30135687, 2018). "Because we have previously shown their permissivity to HIV-1 infection and because of their interactions with dNK cells, we analyzed NK receptor ligand expression at the cell surface of the decidual CD14+ antigen presenting cells (dAPC) and CD3+ T lymphocytes (dLT)." (PMID 22242197, 2012). "In summary, these live cell microscopy experiments support the notion that within non-stimulated PBMC lacking functional SAMHD1, CD14+ monocytic cells are the subpopulation that are highly susceptible to HIV-1 infection." (PMID 22174685, 2011). "Our results indicate that within PBMC from AGS patients, CD14+ cells were the subpopulation susceptible to HIV-1 infection, whereas cells from healthy donors did not support infection." (PMID 22174685, 2011). "The results showed that CD14+ cells were the main targets of HIV-1 infection in the decidua." (PMID 19543402, 2009). "Further substantiating the link between Sn expression and viral load was an observation in a treatment naïve population that Sn mRNA expression in CD14+ monocytes dramatically increased shortly after HIV-1 infection and continued to rise in patients who progressed to AIDS." (PMID 18414664, 2008). "A comparison of the transcriptome of PBMCs from patients with HIV-1 infection and those with HIV-1 and tuberculosis coinfection revealed a higher proportion of the inflammatory CD14+CD16+ monocyte subset in the HIV and tuberculosis coinfection cohort." (PMID 39339847, 2024). "While ARVs preserved CD4+ cell numbers, PDDC reduced CD14+ and CD4+ cell numbers to below those observed with untreated HIV-1 infection." (PMID 37406092, 2023). "In HIV-1-infected BLT mice fed PDDC-containing chow, CD14+ and CD4+ cell numbers were reduced below the levels observed with untreated HIV-1 infection." (PMID 37406092, 2023). "CD3+ CD4+ T helper cells, the main target for HIV-1 infection, as well as CD3+ CD8+ cytotoxic T cells were present at physiological frequencies, and despite their lower repopulation, both CD11b+ macrophages and CD14+ monocytes were present in all major organs." (PMID 30867315, 2019). "During acute HIV-1 infection, the frequency of Foxp3+Helios+CD45RA+ Treg cells was inversely correlated with the frequency of intermediate CD14++CD16+ monocytes, whereas it was positively correlated with the PD-1 density on intermediate CD14++CD16+ monocytes." (PMID 31651258, 2019).
HIV-1 infection (continued). "Using a tissue-specific mixed cell infection model, we demonstrate that while no changes in CD14+ macrophage infection susceptibility were observed, CD4+ T cell HIV-1 infection frequency increases following menopause in the EM, but not CX nor ECX." (PMID 39872519, 2024). "We previously demonstrated that MDM comprised two populations: a non-adherent (CD14+CD4+Siglec-1hi) population refractory to HIV-1 infection and an adherent (CD14+CD4-Siglec-1 l°) population which was highly permissive to HIV-1 infection." (PMID 35534646, 2022). "Funderburg and co-workers in 2012 found that in HIV-1 infection, non-classic (CD14+CD16++) and intermediate (CD14++CD16+) monocytes are increased and also express high levels of tissue factor and P-selectin (CD62P)." (PMID 33968041, 2021). "Here we assessed plasma levels of soluble CD14 (sCD14), C-reactive protein (CRP), IL-6, and intestinal fatty acid binding protein (IFABP) at the pre-infection time point and over the course of the first 45 days of acute HIV-1 infection." (PMID 31937782, 2020). "The expression of PD-1 on non-classical CD14+CD16++ monocytes is positively correlated with the CD4/CD8 ratio during acute HIV-1 infection." (PMID 31651258, 2019). "Furthermore, expression of several other molecules is increased on monocytes after HIV-1 infection, e.g. CD23, CD36, CD14, CD126, HLA-G, and sialoadhesin (and this study)." (PMID 17330143, 2007). "The surface markers analyzed were CD14, a monocyte/macrophage specific marker, HLA-DR (a class II MHC molecule found on antigen presenting cells), CD4, the major receptor for HIV-1 infection, and CCR5 and CXCR4, chemokine receptors which are critical coreceptors essential for HIV-1 entry." (PMID 16623949, 2006). "Individuals with treated or untreated HIV-1 infection also had increased frequencies of CD14 (13.2% ART HIV-1; 19.3%, Untreated HIV-1) and CD16 (5.5%, ART HIV-1; 7.2%, Untreated HIV-1) monocyte populations compared to the CD14 (11.5%) and CD16 (3.6%) monocyte populations in seronegative individuals." (PMID 36175869, 2022). "In addition, the PD-1 density on non-classical CD14+CD16++ monocytes is positively correlated with the frequency of Foxp3+Helios+CD45RA+ Treg cells during acute HIV-1 infection." (PMID 31651258, 2019). "Monocytes are categorized into three subsets: classical (CD14++CD16−), intermediate (CD14++/CD16+), and non-classical (CD14+/CD16++), each playing distinct roles in HIV-1 infection." (PMID 40919207, 2025). "Increased expression of innate restriction factors and cytokine genes were observed in the non-adherent CD14+Siglec-1hiCD4+MDM, both before and after HIV-1 infection, compared to the adherent CD14+Siglec-1LoCD4−MDM." (PMID 29123518, 2017). "We show that CD163 is more highly expressed on CD14++CD16- compared to CD14++CD16+ monocytes, and not expressed on CD14+CD16++ monocytes, at the level of both protein and gene expression, and that expression is increased in HIV-1 infection." (PMID 21625498, 2011). "In contrast, in patients with acute HIV-1 infection, increased proportions of Foxp3+Helios+CD45RA+ Treg were reported along with decreased frequencies of CD14++CD16+ (intermediate) monocytes and increased proportions of PD-1+ cells among both CD14++CD16+ and CD14+CD16++ (non-classical) monocytes." (PMID 37928540, 2023). "During acute HIV-1 infection, the frequency of Foxp3+Helios+CD45RA+ Treg cells is inversely correlated with the frequency of the intermediate CD14++CD16+ monocyte subset, but positively correlated with PD-1 expression in both intermediate CD14++CD16+ and non-classical CD14+CD16++ monocyte subsets." (PMID 31651258, 2019). "mDC (CD1c+), SLAN+ DC and CD14+ monocytes were most efficient in stimulating proliferation of CD4+ T-cells during syngeneic culture and in generating post-integration latent infection in non-proliferating CD4+ T-cells following HIV-1 infection of APC-T cell co-cultures." (PMID 26362311, 2015).
lung cancer (44 papers, 2013 to 2025). A malignant neoplasm involving the lung. "CFSE-labeled lung cancer cells were co-cultured with CD14-labeled human peripheral blood monocyte-derived M1 macrophages." (PMID 40128846, 2025). "It has been reported that Cd14 and Tpd52l1 genes are up-regulated in primary lung cancer compared to the adjacent normal tissue." (PMID 38678138, 2024). "CD14+ cell coculture with lung cancer cell lines H889 and H1581 resulted in CD14+ cell HLA-DR downregulation, a phenotype observed in other models, while the coculture with H1155 did not." (PMID 36139660, 2022). "Promoting tumor recovery appears to be a shared trait of CD14+ cells, as multiple unique healthy donor CD14+ cells were able to improve lung cancer recovery." (PMID 36139660, 2022). "At early stages of lung cancer, as well as in B cell non-Hodgkin lymphoma, CD14+ monocytes exert immunosuppressive properties, which allow them to suppress the cytotoxic activity of T-lymphocytes." (PMID 36104441, 2022). "In vitro studies revealed a bi-directional cross-talk between CD14+ cells and lung cancer that improved lung cancer cell recovery after chemotherapy." (PMID 36139660, 2022). "Previously, CD14+HLA-DRlo/neg cells isolated from lung cancer patients cocultured with a lung cancer cell line resulted in an increased number of viable tumor cells 4 days after a chemotherapy challenge." (PMID 36139660, 2022). "Further work developing CD14 as a prognostic biomarker in early-stage lung cancer will be strengthened by using an external validation cohort, but the similarities between our data and those of the previously published squamous cohort are encouraging." (PMID 36139660, 2022). "Our observations suggest that TME CD14+ infiltration is a prognostic marker in lung cancer and that further studies are needed to understand CD14+-cell-mediated mechanisms that influence patient outcomes." (PMID 36139660, 2022). "Other groups have identified that CD14+ cells imparted targeted therapy resistance to lung cancer cell lines and that an increasing CD14+ cell presence in the TME is associated with a shorter duration of patient benefit with targeted therapy." (PMID 36139660, 2022). "We observed HLA-DR downregulation on CD14+ cells after coculture with lung cancer cell lines, suggesting an immunosuppressive phenotype, as observed in patients with advanced lung cancer and other tumor types." (PMID 36139660, 2022). "In breast and lung cancer, circulating CD14+CD204+ cells are representative for an advanced tumor stage and contribute to metastasis." (PMID 34362423, 2021). "To investigate the function of MoDCs in the immune responses of lung cancer, we generated immature MoDCs by CD14+ monocytes isolated from human PBMCs and matured them using IFN-γ, R848, PGE2, and TNF-α DCs." (PMID 32655564, 2020). "EMSA analysis also revealed that A549- and CL1-5-CM increased the DNA binding activity of STAT3, and laricitrin reduced the lung cancer-induced enhancement of STAT3 on DNA binding capacity in CD14+ monocytes." (PMID 27833081, 2016). "Our study shows that lung cancer cells impair the differentiation of DCs, supported by decreasing CD1a up-regulation and the disappearance of CD14." (PMID 27050278, 2016). "Previously our study showed that lung cancer cells impair the differentiation and function of DCs, which is supported by changing phenotype (decreasing CD1a up-regulation and the appearance of CD14) and expression of high levels of IL-10." (PMID 27833081, 2016). "Both A549- and CL1-5-CM increased the phosphorylation of STAT3, and laricitrin decreased the lung cancer-induced activation of STAT3 in CD14+ monocytes." (PMID 27833081, 2016). "After that, we found in the CD14+ cell population 44 specific miRNAs for lung cancer patients and 26 specific miRNAs for controls." (PMID 25344866, 2014). "Our findings indicate a protective effect of CD14− CD16+ monocytes against lung cancer." (PMID 38408977, 2024).
lung cancer (continued). "The elevated level of CD14− CD16+ monocytes was a protective factor against lung cancer." (PMID 38408977, 2024). "There was no significant change in the proportion of CD3+ T cells and CD3-CD16+CD56+ NK cells (P =0.1427, P= 0.4708) in the best immune status groups of lung cancer compared with the healthy groups, and the p-value of the proportion of CD14+ monocytes was 0.0053." (PMID 38911366, 2024). "Notably, CD163 + CD14+ DCs were found to be abundant in early- and advanced-stage lung cancer primary tissues but less abundant in metastatic lymph nodes and LUAD-BM." (PMID 37760494, 2023). "A previous study indicated that there is less infiltration of these cells in early lung cancer tissues which is consistent with our findings, suggesting that CD14-positive cells predominantly exist in advanced tumors and might related to a poor prognosis." (PMID 36969247, 2023). "Similarly, when CD36+CD14+PANK+ subpopulations isolated from lung-cancer patients were injected into mice, these cells were also found in spleens after 28 weeks, along with unstructured morphology and high levels of TTF-1." (PMID 37427108, 2023). "Furthermore, we demonstrated that the cross-talk between CD14+ cells and lung cancer cell lines resulted in CD14+ cell recruitment, the downregulation of CD14+ cell HLA-DR, and improved cancer cell recovery after chemotherapy exposure." (PMID 36139660, 2022). "Based on these data, we hypothesized that lung cancer cell lines retain the ability to recruit CD14+ cells for a survival advantage." (PMID 36139660, 2022). "Based on the data reported by our group and others, the presence of CD14+ cells within the TME may represent a biomarker for patients with lung cancer across therapeutic approaches and could represent a shared avenue for future therapeutic investigation." (PMID 36139660, 2022). "Collectively, these data suggest that TME CD14+ cell infiltration could inform outcome expectations for patients with lung cancer across treatment paradigms." (PMID 36139660, 2022). "Since increasing CD14+ cells in the lung adenocarcinoma TME was associated with shortened OS and more positive lymph nodes at the time of surgical resection, we developed an in vitro coculture model system to study the interactions between lung cancer cell lines and CD14+ cells." (PMID 36139660, 2022). "CD14+ cell integration into the lung cancer TME can occur early in the disease and may be a promising new therapeutic avenue." (PMID 36139660, 2022). "In conjunction with the previously published data, we believe the presence of CD14+ cells within the lung cancer TME may represent a prognostic marker that could inform treatment expectations across histologies and treatment approaches." (PMID 36139660, 2022). "Similarly, in our patient cohort with lung adenocarcinoma, the higher levels of CD14+ TME infiltration were associated with a higher number of tumor-bearing lymph nodes at the time of surgery and shorter lung cancer-specific survival." (PMID 36139660, 2022). "In vitro studies utilized a coculture system to model the lung cancer TME containing CD14+ cells." (PMID 36139660, 2022). "Gaining a better understanding of how and which phenotype of CD14+ cells influence tumor survival may help personalize the currently available lung cancer therapy and drive new therapeutic strategies." (PMID 36139660, 2022). "In addition, we collected CD14+ monocytes from peripheral blood mononuclear cells (PBMCs) of lung cancer patients and healthy controls (HCs), and differentiated them into macrophages via incubation with M-CSF." (PMID 33175182, 2021). "MPE-Mφ collected from lung cancer patients were identified as CD14+ CD68+ macrophages." (PMID 33175182, 2021).
lung cancer (continued). "Further characterization of the MDSC subsets that are present in lung cancer patients revealed that, while CD14+ expressing M-MDSC derived from both Ctrl and DEX-treated patients are increased, the in vitro suppressive function of M-MDSC was more potent in DEX-treated patients." (PMID 30537999, 2018). "Therefore, the ratio of CD1a/CD14 is a critical indicator for assessing the differentiation degree of DCs in lung cancer." (PMID 27050278, 2016). "Therefore, IL-10 expression and CD1a/CD14 ratio are critical indicators for assessing the degrees of differentiation and function of DCs in lung cancer." (PMID 27833081, 2016). "As a comparison, the proportions of CD3+T cells, CD14+ monocytes, and CD3-CD16+CD56+ NK cells in the lung cancer patients with the poorest immunological function were significantly different from those in the healthy control group (P <0.0001)." (PMID 38911366, 2024). "CD14+ mononuclear macrophages were infected with ZBP1-U, ZBP1-M, shZBP1, or control lentivirus and mixed with A549 lung carcinoma epithelial cells." (PMID 38369516, 2024). "Furthermore, we only revealed a preliminary correlation among lung cancer intestinal microbiota, metabolites, and proteomics, but the causal relationship among P. copri‐nervonic acid and all‐trans‐retinoic acid‐CRP, LBP, and CD14 axis needs further investigations." (PMID 35735103, 2022). "At the baseline, the lung cancer cell lines were releasing detectable levels of CCL2, a potent chemokine for CD14+ cells." (PMID 36139660, 2022). "For lung cancer, the main body of literature reports increases of monocytic CD33+CD11b+CD14+ MDSCs or granulocytic-like CD33+CD11b+CD14− MDSCs." (PMID 32849585, 2020). "We first compared the significant miRNAs identified in the comparison of cells derived from myeloid progenitors (CD15+, CD14+) versus cells derived from lymphoid progenitors (CD3+, CD19+, CD56+) of lung cancer patients and controls." (PMID 25344866, 2014). "Furthermore, the THC-specific cell surface signature (CD36+CD14+PANK+) enables the identification of these cells in matched primary tumour tissues and metastases, as well as in the bloodstream of patients with lung cancer, acting as a biomarker." (PMID 39967663, 2025). "This shared observation underscores the need to validate TME CD14+ infiltration as a prognostic marker in lung cancer, and for further studies to identify the immune and non-immune mechanisms by which CD14+ cells influence patient outcomes." (PMID 36139660, 2022). "Within the lung cancer TME, CD14+ cells may also influence T-cell responses by expressing immunosuppressive T-cell checkpoints, as was noted in a subset of 61 patients with early and more advanced stage resected NSCLC of either histology." (PMID 36139660, 2022). "Additionally, in vitro, we approximated the lung cancer TME containing CD14+ cells and demonstrated that CD14+ cells reduce chemotherapy-induced cancer cell death." (PMID 36139660, 2022). "Our observation that intermediate monocytes (CD14+CD16+) with CD11c+ and HLA-DR+ expression correlation with the amount of macrophages from the lung cancer microenvironment may indicate role a of these cells in cancer immunity." (PMID 32899681, 2020). "Furthermore, the comparison of antigen presenting cells (CD19+, CD14+) with cytotoxic cells (CD3+, CD56+) revealed 47 miRNAs significantly deregulated in lung cancer blood samples and 37 miRNAs in blood samples from healthy individuals." (PMID 25344866, 2014). "Although the data demonstrate that exposure of healthy donor PBMCs to lung cancer cell lines increases CCL3, IL8 and IL1β production by CD3+ and CD14+ PBMC fractions, it remains unclear as to the specific interaction which causes this result." (PMID 23762239, 2013).